RNU6-421P (RNA, U6 small nuclear 421, pseudogene)
Gene: Small nuclear RNA gene on chromosome X (49,945,336 to 49,945,442, reverse strand). Ensembl gene ENSG00000201341.
Homologues: Orthologues: chimpanzee U6 (100% identical), macaque U6 (99% identical), dog U6 (77% identical), pig U6 (75% identical), mouse Gm24593 (73% identical), rat LOC120101183 (72% identical), mouse Gm55921 (60% identical). Paralogues in human: RNU6-543P (82% identical), RNU6-944P (80% identical), RNU6-1050P (79% identical), RNU6-380P (79% identical), RNU6-753P (79% identical), RNU6-79P (79% identical), RNU6-1091P (79% identical), RNU6-181P (79% identical), RNU6-43P (79% identical), RNU6-454P (79% identical), RNU6-657P (79% identical), RNU6-658P (79% identical), and 1285 more.